MET (MET proto-oncogene, receptor tyrosine kinase)
Diseases named in the same sentence as MET in open-access papers (continued):
Sharing a sentence is not in itself a finding about the gene and the disease.
tumor (continued). "However, precision medicine successes are not straightforward, for example, before Crizotinib was licenced for use in ALK translocations, it was originally tested in MET mutated tumours." (PMID 35941175, 2022). "In recent years, a lot of evidence has indicated that MET inhibitors have a good anti-tumor effect in patients with MET exon 14 skipping mutation, suggesting that MET exon 14 skipping may be a new target for NSCLC patients." (PMID 33921709, 2021). "The depletion or inhibition of c-MET could suppress the tumor growth and metastasis caused by the low expression of DNM3." (PMID 34490234, 2021). "Given the presence of a targetable gene fusion, the presence of residual tumor, and the morbidity associated with additional surgery or radiation, the patient was subsequently treated with the MET inhibitor cabozantinib and demonstrated a complete pathological response." (PMID 34863095, 2021). "Tumours overexpressing c-MET are associated with poor survival rates." (PMID 33816276, 2021). "Tumours can grow and metastasize due to dysregulation caused by aberrant c-MET activation." (PMID 34203771, 2021). "Moreover, JNJ-61186372 downregulated receptor expression on tumor cells thus preventing the drug resistance mediated by new emerging mutations of EGFR or c-MET." (PMID 32989604, 2020). "The effect of c-MET on tumor associated leukocytes and cancer outcomes is worthy of further exploration as it may be possible to target leukocytes with c-MET inhibitors." (PMID 32117721, 2020). "The HGF/MET signalling pathway is one of the major causes of tumor cell migration." (PMID 32843066, 2020). "In addition, hypoxia in tumor tissues caused by the inhibition of VEGFR has been reported to induce the expression of MET and contribute to the resistance to VEGFR inhibition." (PMID 31820255, 2020). "Furthermore, high expression of HGF or c-MET was associated with higher histological tumor grade and worse patient outcomes." (PMID 32188473, 2020). "STRING network analysis show that Sema4D interacts with the tumorigenesis-associated protein MET, and that it may have roles in multiple processes such as apoptosis during tumor formation and immune functions in chickens." (PMID 31394878, 2019). "Since cancers usually have a high proportion of proliferative cells and are associated with a hypoxic environment, inhibition of tumor growth by AXL/MET inhibitors might decrease their oxygen demand." (PMID 31781483, 2019). "Meanwhile, results of the tumor sequencing indicated the expression of mutation of the MET gene." (PMID 30474572, 2018). "In addition, the expression of MET was higher in tumour‐associated macrophages in the H. pylori‐infected human GC tissues." (PMID 30160350, 2018). "Indeed, tumor cells addicted to aberrant RTK expression such as MET-amplified GCs and EGFR-mutated NSCLCs were highly sensitive to M-COPA, and these RTKs were effectively downregulated by M-COPA treatment." (PMID 29416720, 2018). "To determine whether SEMA3C can drive activation of EGFR and MET signaling in other cell types, we first screened cBioPortal for Cancer Genomics data for tumor types that showed an association of high SEMA3C expression and poor prognosis." (PMID 29348142, 2018). "Sequencing of his tumor evidenced a mutation of the MET gene." (PMID 30474572, 2018). "Moreover, oncogenic c-MET signaling is associated with poor survival and increased tumor invasiveness in GBM patients." (PMID 28821904, 2018).
tumor (continued). "To better understand the mechanisms underlying the observed exosomal MET‐mediated effects on macrophage function and, subsequently, GC progression, we focused on changes in inflammatory mediators known to play a role in the tumour microenvironment." (PMID 30160350, 2018). "Treatment of GC cells with supernatant from macrophages incubated with MET+ exosomes caused a substantial increase in volume and weight of the resulting xenograft tumours compared to tumours formed from GC cells treated with supernatant from macrophages incubated with PBS or MET− exosomes." (PMID 30160350, 2018). "Thus, dysregulation of the MET signaling pathway has been implicated in the pathogenesis of cancer, such as tumor cell proliferation and survival, invasion, and metastasis." (PMID 29088885, 2017). "MET membranous overexpression was associated with a significantly higher tumor response." (PMID 27014419, 2016). "As the HGF/MET signaling pathway plays a role in several key processes underlying tumor progression, targeting this pathway is considered a promising therapeutic strategy for the treatment of patients with MET-expressing cancers, including those with NSCLC who have acquired resistance to EGFR TKIs." (PMID 27422720, 2016). "MET protein expression was observed in pre-existent basal and atrophic luminal glandular epithelium, which served as internal positive controls, and was variably expressed in both normal and tumor-associated endothelial cells." (PMID 27105539, 2016). "However, in the TCGA dataset, encompassing 401 GBMs analyzed by whole tissue transcriptional profiling, high MET expression in the primary tumor was significantly associated with decreased disease‐free and overall survival." (PMID 27138567, 2016). "This tumour is characterised by the presence of a specific chromosomal translocation encoding the chimeric transcription factor (ASPL-TFE3) that activates expression of MET." (PMID 26284114, 2015). "The information presented indicates that circulating HGF and MET levels, MET protein expression levels in tumor tissues, and MET gene amplification, copy number and mutation, as well as markers related to crosstalk of related pathways, are commonly evaluated biomarkers." (PMID 28536405, 2015). "To determine whether MET overexpression or mutation was sufficient to induce tumor formation and invasion in-vivo, we established tumor xenograft models in human HGF transgenic mice on a severe combined immunodeficiency (SCID) background, named hHGF Tg SCID." (PMID 25605252, 2015). "They convincingly demonstrated that deletion of MET in neutrophils was associated with increased tumor growth and metastasis in multiple tumor models in mice, including spontaneous mammary tumors driven by transgenic expression of the polyoma virus middle T (PyMT) antigen." (PMID 26438048, 2015). "It is possible that evaluation of the HGF/c-MET signaling axis in the tumor may indicate the susceptibility of that tumor to show resistance through this pathway." (PMID 26090722, 2015). "Certain c-MET mutations are found to be germline with unknown transforming activity while others are implicated in driving neoplasia." (PMID 26097886, 2015). "In addition to HGF and MET overexpression, this pathway can also be activated through genetic alterations such as MET-activating mutations that, although rare in all tumor types, are certainly contributing to carcinogenesis." (PMID 26319934, 2015). "Similarly for HGF, deregulated HGF/MET signaling is a common hallmark of many tumors and is associated with various aspects of tumor progression." (PMID 26100469, 2015). "The current understanding is that high MET protein expression levels in tumor tissues may be associated with poor patient survival in selected cancer types." (PMID 28536405, 2015). "Polymorphisms of c-MET which on their own may lack transformative ability may still play a role in promotion of tumor development and metastasis in combination with other mutations." (PMID 26097886, 2015).
tumor (continued). "Patient 19 (DSRCT) also demonstrated a c-MET N375S mutation in his tumor tissue." (PMID 25119929, 2014). "In CRC, overexpression of MET has been suggested to be associated with tumor progression." (PMID 24500024, 2014). "c-MET high expression was more associated with intestinal than diffuse tumor type (P = 0.04), deeper tumor invasion, pT3 and pT4 versus pT1 and pT2 (P = 0.014), neural invasion (P = 0.002) and advanced TNM staging, stage 3 and 4 versus stage 1 and2 (P = 0.044)." (PMID 22640970, 2012). "Amplification of MET may thus define a subgroup of tumours that are susceptible to targeted kinase inhibition." (PMID 21847121, 2011). "The c-Met protein is expressed mostly in in mammalian tissues and plays an important role in different cellular process; its ligand is the HGF (Hepatocyte Growth Factor), known also as Scatter Factor (SF) and c-MET over-expression or inactivation is implicated in different tumoral disease." (PMID 19949545, 2009). "Daily treatment with the MET inhibitor SU11274 caused statistically significant interval retardation of the xenograft tumour growth of H1975 cells with a ninefold reduction (P=0.0251) in the xenograft growth, when compared with the diluent control, during the treatment period." (PMID 19238632, 2008). "In vivo experiments further confirm our hypothesis that MET plays a role in tumour formation, showing that cells overexpressing WT or mutated MET can indeed form tumours within 12 days after injection." (PMID 15785735, 2005). "Specifically, the authors examined c-MET receptor expression in both tumor samples and cultured cancer cells, and they found that poorly differentiated cell lines frequently expressed high levels of the receptor and that high c-MET levels were associated with increased motility and invasiveness." (PMID 40361420, 2025). "Consequently,this enables it to suppress the carcinogenic effect mediated by β‐catenin,effectively overcoming acquired resistance to EGFR‐TKIs caused by MET amplification in both cell line‐derived and patient‐derived tumor xenograft (PDX) mouse models while maintaining exceptional biosecurity." (PMID 38867713, 2024). "Finally, the risk score was calculated by the following formula: tumor-associated endothelial signature score = 0.180855332*ADD1 + 0.059530341*ALOX12 + 0.145361104 *CXCL10 - 0.081730252*F2RL1 + 0.001225741*ITGAX − 0.004914148*MET." (PMID 37719845, 2023). "They found that tandem duplication of the mutated MET allele occurred in almost 50% of the tumor cells, indicating that the acquired resistance to MET inhibitor PF-04217903 might be related to an increase in the copy number of the gene with the mutated MET allele." (PMID 35619895, 2022). "Assuming that the driver mutations in genes such as EGFR, ALK, ROS1, HER2, and MET (among others) had demonstrated advantages favoring cell transformation, leading to the expansion of the altered clone, which could be followed by tumor formation and its evolution." (PMID 36430388, 2022). "Experiments using immortalized cell lines and patient-derived xenografts have illustrated that tumors harboring MET mutations and amplifications are responsive to MET blockade in the form of cell cycle arrest and/or apoptosis in vitro and complete inhibition of tumor growth in vivo." (PMID 35326642, 2022). "EGFR and MET belong to members of the RTK family, and MET, the tyrosine kinase transmembrane receptor for MET, is a protein product encoded by the c-MET proto oncogene that has been of interest in the clinic as a potential therapeutic target in multiple tumor types." (PMID 35227278, 2022). "However, mutations in oncogenic drivers such as EGFR, ALK, BRAF, or MET modify the immune tumor microenvironment and may promote anti-PD1/PD-L1 resistance." (PMID 34208111, 2021).
tumor (continued). "In addition, differences in MET among the primary tumor, peripheral lesions, and brain lesions might guide the treatment as some MET mutations lead to resistance to gefitinib but may still respond to crizotinib." (PMID 31944608, 2020). "Notably, the increased metastasis induced by pericyte depletion can be limited by additional MET or Ang2 inhibitors, which may provide a new and efficient strategy to suppress tumor growth while minimizing the risk of metastasis." (PMID 29560266, 2018). "Beyond the outgrowth of mutant BRAF, we identified two additional genetic alterations in the resistant tumor that could contribute to EGFR TKI resistance: focal amplification of 7q31.2 encoding MET in the resistant tumor cells, a low frequency EGFRT790M mutation (14% variant frequency)." (PMID 28287179, 2017). "However, it is possible that the aggressive tumor phenotype associated with MET expression might have contributed to the limited single-agent activity of emibetuzumab." (PMID 29071414, 2017). "Although MET mutations happen rarely in cancers, they may correlate with tumor development." (PMID 27013592, 2016). "MET mutations occur only rarely in cancers, but may correlate with tumor development." (PMID 27013592, 2016). "We sought to investigate the demographics and tumor-associated features in patients with gastroesophageal (GE) malignancies referred to our Phase I Program who had formalin-fixed, paraffin-embedded tissue from archival or new biopsies tested for MET mutation and/or amplification." (PMID 24742823, 2014). "Downstream effectors of HGF/c-MET signalling regulate proliferation, survival and metastasis and hence facilitate tumour progression." (PMID 41476776, 2026). "Dietary protein restriction in both the DEN/PB and the c-MET/β-catenin models greatly reduced the ammonia burden and slowed tumor progression." (PMID 41512056, 2026). "Preclinical studies have demonstrated that AR suppression, tumor hypoxia and tumor-microenvironment interactions promote MET upregulation, supporting AR-independent growth and epithelial-to-mesenchymal transition." (PMID 42122259, 2026). "Taken together, we generated two novel TCEs targeting c-MET, and the comparison of the scDb and taFv formats showed equal efficacy of specific cell binding and T cell-mediated tumor cell killing for this target in vitro." (PMID 41552759, 2026). "LINC00240 and miR-101 modulate this pathway through HGF/c-MET or its downstream effectors, which affect tumour cell viability and invasion." (PMID 41476776, 2026). "Receptor tyrosine kinases (RTKs), including VEGFR-2, EGFR, and c-MET, have been recognized as promising oncogenic targets in tumor progression, invasion, and metastasis." (PMID 41658091, 2026). "c-MET exhibited significantly higher expression at the tumor front versus tumor center, along with notable intratumoral heterogeneity." (PMID 41837391, 2026). "These tumors often acquire a more invasive phenotype and require dual VEGF and MET inhibition to synergistically induce prolonged anti-tumor response." (PMID 39858062, 2025). "MYC silencing on the other hand has the opposite effect, slowing tumor progression, and when performed in combination with MET inhibition, it resensitizes resistant models to TKIs." (PMID 39858062, 2025). "Here we have shown examples of recurrent in-frame fusion genes with the kinases CDK12 and MET as 3’ partners, fusions that have previously also been found in tumour samples." (PMID 41421967, 2025).
tumor (continued). "Transcriptomic analysis reveals strong correlations between MET overexpression, PD‐L1 levels, and phosphorylated STAT4, indicating a MET/STAT4/PD‐L1 axis that reprograms tumor‐associated macrophage (TAM) phenotypes." (PMID 40654157, 2025). "Mesenchymal-epithelial transition factor (c-MET), the tyrosine receptor for hepatic growth factor (HGF), has been implicated in tumor cell proliferation and survival." (PMID 40380992, 2025). "Collectively, these findings reinforce that tumor‐intrinsic PD‐1 is both a prognostic biomarker and a molecular correlate of MET signaling activation in PDAC." (PMID 40673866, 2025). "MYTX‐011 represents a novel advancement in ADC technology, leveraging the engineering of the antibody component to enhance tumour targeting and therapeutic efficacy in cancers expressing c‐MET." (PMID 40619749, 2025). "According to the literature, heat at a certain range often induces tumor growth of HCC by activating MET and EGFR signals, extracellular collagen I-mediated ERK signal, or VEGF/VEGFR1 signal." (PMID 41173836, 2025). "For example, co-targeting alternatively activated pathways, such as MET amplification, has demonstrated an enhanced anti-tumor effect of gefitinib." (PMID 40025612, 2025). "Tumor-associated stromal cells (CAFs) secrete growth factors such as the hepatocyte growth factor (HGF), which activates the MET pathway." (PMID 40002260, 2025). "CAR T‐cell therapies for PM have primarily targeted several specific tumor‐associated antigens, including MSLN, placental alkaline phosphatase‐like 2 (ALPPL2), fibroblast activation protein (FAP), and MET." (PMID 40904706, 2025). "HGF/c-MET signaling fosters the transition of TAMs from the M1 phenotype (anti-tumor, pro-inflammatory) to the M2 phenotype (pro-tumor, immunosuppressive)." (PMID 40281554, 2025). "This review highlights key MET alterations, such as gene amplification, gene fusions, and exon 14 skipping deletions, and examines their prevalence across various tumor types." (PMID 40361420, 2025). "Regarding our findings, several hub genes, including ADAM12, MET, THBS2, ZEB1, and ZEB2, have been previously implicated in PDAC progression, tumor invasiveness, and epithelial–mesenchymal transition (EMT)." (PMID 40728965, 2025). "Treatment with PHA-665752, a MET (MET encoding HGF receptor) inhibitor, significantly reduced NEBC tumor growth." (PMID 40893664, 2025). "In contrast, it shows a negative correlation with ATRX, a gene linked to TMZ resistance, and also with tumour‐growth‐promoting genes like BRAF and MET." (PMID 40662483, 2025). "Inspired by these results, we also examined the level of p-c-MET in tumor cells following treatment with the AS1411-SL1 chimeras at varied concentrations ranging from 100 to 1000 nM." (PMID 39744222, 2025). "When the c‐MET pathway is abnormally activated in tumour tissue, it can promote the proliferation and metastasis of tumour cells." (PMID 41190648, 2025). "In this case, the development of HPD was associated with a high postoperative tumor burden, elevated PD-1 expression, and aberrant activation of signaling pathways mediated by EGFR, MET, and FGFR1 amplifications." (PMID 40575167, 2025). "In cohort D of the CHRYSALIS-2 trial, MET immunohistochemistry (IHC) positivity, defined as MET 3+ staining on at least 25% of tumor cells, was observed in 36% of the available pre-treatment tissue biopsies." (PMID 40725428, 2025). "Preclinical evidence indicates that MET signaling contributes to radioresistance through enhanced DNA repair, activation of prosurvival pathways, and promotion of tumor proliferation." (PMID 41573491, 2025). "PRO-6E effectively downregulated key downstream signalling proteins, including c-Myc and phosphorylated ERK, reinforcing its potential to inhibit tumour proliferation and metastasis through targeted MET degradation." (PMID 40793752, 2025).